BCL2 (BCL2 apoptosis regulator)
Diseases named in the same sentence as BCL2 in open-access papers (continued):
Sharing a sentence is not in itself a finding about the gene and the disease.
tumor (continued). "In vivo experiments confirmed that such nanoparticles were accumulated into the tumour and reduced the inhibition of tumour growth and the Bcl-2 expression." (PMID 29415514, 2018). "In tumors, VEGF is the most important angiogenic factor, and inhibits tumor cell apoptosis by inducing the anti-apoptotic protein Bcl-2." (PMID 30305062, 2018). "Generally, in most tumor cells, the mitochondrial membrane potential is controlled by anti-apoptotic genes (e.g., bcl-2, bcl-XL) and pro-apoptotic genes (i.e., bax)." (PMID 29518056, 2018). "MjTX-I exerts selective cytotoxicity against leukemic cell lines, with low toxicity towards non-tumor cells, and induces apoptosis accompanied by caspases activation and downregulation of BCL-2 and upregulation of BAD expression." (PMID 30598659, 2018). "In vivo, co-administration of the Bcl-2 inhibitor GDC-0199 significantly potentiated ABC294640-induced anti-C33A tumor activity in nude mice." (PMID 29416779, 2018). "Venetoclax was the first BCL-2-selective agent to enter the clinic and quickly showed signs of anti-tumor activity." (PMID 30406027, 2018). "Immunohistochemical staining for Ki67 and Bcl2 showed reduced levels of tumor proliferation and growth in osthole-treated mice." (PMID 30577812, 2018). "The expression Bcl2 was significantly increased in tumor homogenate in comparison with normal control tissue (p≤0.001)." (PMID 31098389, 2018). "We further report that genetic or pharmacological inhibition of USP13 considerably reduces MCL1 protein abundance and significantly increases tumor cell sensitivity to BH3 mimetic inhibitors targeting BCL-2 and BCL-XL." (PMID 29335437, 2018). "Regarding dietary fiber, a polysaccharide from Lentinus edodes mushroom suppressed tumor growth in nude mice, upregulated caspase-3, -9 activity, increased Bax/Bcl2 ratio, increased the generation of free radicals in tumor tissues and TNF-α production." (PMID 30487390, 2018). "The decrease in tumor flux seemed to be more substantial in mice that received Bcl-2-expressing NSCs, so we calculated the average % increase in luminescence flux that occurred in each treatment group." (PMID 30026762, 2018). "Downregulation of miR-365, a tumor suppressive miRNA, increases cancer cell proliferation, therapeutic resistance, and decreases apoptosis by disinhibiting expression of Cyclin-D1, BCL-2, and PI3K, while decreasing expression of PTEN." (PMID 30546829, 2018). "STAT1−/− mice showed elevated colonic epithelial cell proliferation in early stages of injury-induced tumor formation and decreased apoptosis in advanced tumors with over-expression of the anti-apoptotic protein Bcl2 at the colon." (PMID 30235866, 2018). "LMP1 can also inhibit the apoptosis of tumor cells by inducing the expression of anti-apoptotic genes A20 and Bcl-2." (PMID 29920566, 2018). "Taken together, PPARα/Bcl2/autophagy signaling promoted autophagy and enhanced tumor suppression and chemotherapy sensitivity to cancer cells." (PMID 30519260, 2018). "From day 14, there were significant differences in the Δ% of Bcl-2, apoptosis and tumor necrosis in the sensitive vs. control or insensitive group." (PMID 30518386, 2018). "Disturbance of the ratio of Bax/Bcl-2 was found in the tumor tissues after kurarinone treatment, which was in accordance with the in vitro results." (PMID 29628889, 2018). "The results showed that EAEO treatment significantly enhanced apoptotic nucleus in the tumor sections, suppressed the ratio of Bcl-2/Bax and increased the expression of cleaved caspase-9 and -3." (PMID 29867489, 2018). "We also determined the apoptosis by ELISA assay and RT-PCR method of BAX, Bcl-2, and Caspase 3 levels in tumor tissues of H22 tumor-bearing mice and SMMC-7721 cells." (PMID 29636773, 2018). "On the other hand, Bcl-2 (B-cell lymphoma 2) protein promotes tumor cell survival by inhibiting the actions of pro-apoptotic proteins." (PMID 29958416, 2018).
tumor (continued). "The average weights of tumors were 0.77 ± 0.12 gm and 2.24 ± 0.33 gm for experimental and control groups, respectively, and the rate of tumor growth with Bcl-2-siRNA treatment was 14.99% compared to 45.58% in the control group." (PMID 29861465, 2018). "Here we show that hyperosmotic stress in the tumor microenvironment unleashes the deadly potential of DRs by enforcing BCL-2 addiction of cancer cells." (PMID 29706657, 2018). "In this study, the expression of Bcl-2, Bax, caspase-3, caspase-8 and caspase-9 in tumor tissues were detected by western blotting, and the cell cycle makers and apoptotic index of tumor cells were detected by flow cytometry." (PMID 30670974, 2018). "Co-administration of the Bcl-2 inhibitor GDC-0199 further potentiated ABC294640's anti-tumor activity." (PMID 29416779, 2018). "“Double-hit score,” representing IHC-based evaluation of tumor cell expression of BCL2 and MYC, showed that 10/76 (13%) cases were positive for both MYC and BCL2." (PMID 28302137, 2017). "Following DEN/PB-exposure Bcl-3Hep mice showed a significantly reduced mRNA expression of anti-apoptotic factors including Xiap (p < 0.001), Bcl2l1 (p < 0.05) and Bcl2 (p < 0.05) in the liver in parallel to increased rates of apoptosis in tumor tissue." (PMID 28915576, 2017). "Diverse anti-apoptotic proteins as Bcl-XL, Bcl-2, Bcl-w, and Mcl-1 can prevent cell death in tumor cells." (PMID 28352231, 2017). "From six tumour-bearing mice (n = 6) of each treatment group, TIFFalyzer and IHC Profiler quantitative immunohistochemical analysis for the level of expression of bcl-2 and cox-2 was performed as described in methods." (PMID 29156646, 2017). "The Bcl-2/Bax ratio in tumor tissues was also decreased after sesamol treatment, which is consistent with our in vitro study." (PMID 28374807, 2017). "Bcl-2 can prevent cell death via the mitochondrial apoptosis pathway, and overexpression of Bcl-2 would render the tumor cells resistant to anticancer drugs." (PMID 28383524, 2017). "Consistently, we found that juglanin up-regulated Bax and Bad expression, while Bcl-2 and Bcl-xl were down-regulated in cells and tumor samples." (PMID 29212196, 2017). "The results of in vivo studies suggest that Bcl-2/Twist1 depletion can, to a great extent, inhibit tumor growth and metastasis." (PMID 28032603, 2017). "Accordingly, miR-204 suppresses tumor cell growth, apoptosis and survival by targeting Mcl-1, Bcl-2 and TrkB, impacted tumor migration, invasion and metastasis by targeting FOXC1 and slug." (PMID 28388577, 2017). "Similar to what was observed in vitro, the expression levels of Bcl-2, Bcl-xL and survivin proteins were down-regulated in tumor tissue from drug-treated animals as detected by immunohistochemistry." (PMID 28415735, 2017). "In vitro, the co-delivery nanocarriers suppressed the expression of anti-apoptosis gene Bcl-2 at both transcription and protein levels, inhibited tumor cell migration and efficiently induced cell apoptosis and cytotoxicity." (PMID 28383524, 2017). "Numerous studies have shown IL-22 promotes tumor progression through up-regulating Bcl-2 protein expression." (PMID 28445985, 2017). "In the monoculture condition, compared with doxorubicin and cisplatin, the IC50 of ABT-199 in SU-DHL-8 was unachievable, confirming that the cytotoxic effect of ABT-199 relied on Bcl-2 expression in tumor cells." (PMID 28637496, 2017). "Immunohistochemical (IHC) and TUNEL analyses were used to analyse the level of COX-2, PAS, AR, and Bcl-2 expressions and we observed the apoptosis of tumour cells in both model, and treatment, groups." (PMID 28383015, 2017).
tumor (continued). "In their study, Bcl-2 can bind to Twist1 and formation of the Bcl-2/Twist1 complex facilitates the nuclear transport of Twist1 and increase the tumor cell plasticity, metastasis, and vasculogenic mimicry." (PMID 28032603, 2017). "Bcl2 expression in the tumor cells were further decreased in cells with miR-125b-5p and cisplatin treatment." (PMID 28256505, 2017). "The expression of BNIP3 was associated with increased apoptosis, decreased cellular proliferation, increased Bax and decreased Bcl-2 levels in the tumor tissues." (PMID 28968982, 2017). "Bcl-2 is a tumor suppressing gene, regulating mitochondrial membrane permeability to inhibit the signal transduction pathway of cell apoptosis." (PMID 28261501, 2017). "A western blot assay showed that rLj-RGD3 reduced the level of Bcl-2, but increased the level of cleaved caspase 3 in the tumor tissues of the HeyA8 xenografted mice." (PMID 29244724, 2017). "The Bcl-2/Twist1 complex facilitates Twist1 nuclear transport and leads to transcriptional activation of a wide range of genes that induce tumor cell EET and VM." (PMID 27034014, 2017). "With a P-value threshold at 0.05, only 3 genes (BCL6, BCL2, and HIST1H2BM), containing the regulatory mutation blocks, show significant differential expression between the tumor and normal samples." (PMID 28765546, 2017). "To further reveal the pro-apoptosis mechanism, we performed immunohistochemistry analysis to detect the protein level changes of Bcl-2 and caspase-3 in tumor tissues." (PMID 28212270, 2017). "Tumor suppressor miRNAs repress the oncogenes that induce tumor proliferation, resistance and metastasis; for example, miRNA-15 and 16 are strong inhibitors of the anti-apoptotic protein Bcl-2." (PMID 28825675, 2017). "We developed a Tca8113 xenograft tumor model by injecting tumor cells in the mouth floor to confirm the consequence of silencing Bcl-2/Twist1 in vivo." (PMID 28032603, 2017). "It should be noted that the focus of the present study was germline BCL2 genotypes, therefore all analyses were performed in non-tumor tissue." (PMID 28396899, 2017). "Our results are consistent with studies showing that both BCL-XL and BCL-2 are key regulators of the angiogenic crosstalk between tumor and neovascular endothelial cells." (PMID 29238043, 2017). "Quantitative levels of bcl-2 expression and inter-treatment comparisons for the tumour samples from all treated groups are presented in the following tables." (PMID 29156646, 2017). "The results show that DMABTSPd(TSPd) led to the increase at Bid level (**P < 0.01, vs DMSO-group), and the decrease at Bcl-2 level in a nude mouse tumor xenograft model (**P < 0.01, vs DMSO-group)." (PMID 28099141, 2017). "Considering tumor lesions and apoptotic markers expression, Bcl-2 was more expressed in malignant tumors (P<0.01 for positive cells intensity and IRS scale) than in benign tumors and in healthy tissue." (PMID 28081183, 2017). "More recently, a number of small molecules like pyridostatin analog, metal complexes, quindoline derivatives, with high affinity to bcl-2 G-quadruplex DNA have been reported to inhibit the transcription of Bcl-2 and thus inducing apoptosis of tumor cells." (PMID 28531122, 2017). "MIAs can induce apoptosis in tumor cells through several mechanisms, such as blocking the cell cycle, inhibiting the phosphorylation of Bcl-2 and Bcl-xl, activating caspases, upregulating E2F1, and causing the release of cytochrome c." (PMID 29069746, 2017). "Both patients developed refractory diseases within 1 year after diagnosis that were accompanied by MYC and BCL2 rearrangements in their tumor cells." (PMID 28055963, 2017). "VEGF also supports tumor growth by protecting tumor neovasculature against apoptosis, through induction of the anti-apoptotic factors, Bcl-2 and survivin." (PMID 28030810, 2017).
tumor (continued). "Results showed that the expression level of proapoptotic protein Bax in tumor tissue was significantly elevated while expression of antiapoptotic Bcl-2 protein was effectively reduced, resulting in an increased Bax/Bcl-2 ratio." (PMID 29348766, 2017). "Bcl-2 is considered a favorable prognostic marker in multiple tumor subtypes, particularly ER-positive breast cancer." (PMID 29254147, 2017). "The tumor specimens were examined using immunohistochemistry, and results showed the level of Bcl-2 and YAP were down-regulated, but the expression of PTEN and PI3K was upregulated in the FR5-treated groups." (PMID 29299170, 2017). "For example, MicroRNA-30b can function as a tumor suppressor in CRC by targeting KRAS, PIK3CD and BCL2, while MicroRNA-224, a tumor promoter, targets PHLPP1 and PHLPP2, sustains Wnt/β-catenin signaling and promotes aggressive phenotype of CRC." (PMID 29118671, 2017). "ABT-199 directly targeted Bcl-2 on endothelial cells, induced endothelial cell apoptosis and inhibited tumor angiogenesis." (PMID 28637496, 2017). "Here, Bcl-2 was just regarded as an indicator of cell survival, which partly accounts for IL-22-induced tumor growth." (PMID 28445985, 2017). "The IOD value of COX-2, PAS, AR, Bcl-2 and Caspase-3 expression value of tumor tissues in each groups were determined by IHC analyzing using IPP software." (PMID 29029409, 2017). "After treatment with berberine, the expression of PSA, AR, COX-2 and Bcl-2 were significantly reduced and the expression of Caspase-3 was significantly increased in tumor samples." (PMID 29029409, 2017). "The increased Bax and decreased Bcl-2 in the tumor lysates from chaetocin-treated mice were also observed with the activation of caspase-9/-3, which is closely associated with chaetocin-induced apoptosis." (PMID 28419143, 2017). "The aim of our study was to investigate the qualities of the new delivery system comparatively to a commercially formulation in use, after local application on the tumour, using as control parameters the expression level of bcl-2 and cox-2 proteins." (PMID 29156646, 2017). "Depending on tumor type and disease stage, as well as therapy, BCL2 seems to be able to act as both an oncogene and a tumor suppressor gene." (PMID 28396899, 2017). "Decreased miR-143 expression was detected in CC tissues and introduction of miR-143 suppressed tumor formation in CC cells through suppressing Bcl-2 expression." (PMID 29073938, 2017). "Immunohistochemical analysis with tumor xenografts verified the results of Western blotting with culture cells, showing similar expression patterns of Bax, Bcl-2, and Bcl-xL between culture cells and tumor xenografts." (PMID 28212569, 2017). "Oncogenic Bcl-2 is activated by the inactivation of miR-204, thus supporting its tumor suppressor role in GC." (PMID 29283424, 2017). "It has been demonstrated that cell survival-associated Bcl-XL and Bcl-2, proliferation-associated CyclinD1, and VEGF are involved in the promotion effect of IL-22 on tumor." (PMID 28445985, 2017). "Tumor proliferation, expressed as the ratio of Bcl-2 mRNA copy number to that of Bax, is found to be inversely proportional to the decrease of rpL3 gene expression and increased with tumor grade." (PMID 28085118, 2017). "It is increasingly apparent that prosurvival proteins provide a strong buffering capacity against the BOPs that accumulate upon ERK1/2 inhibition; indeed, prosurvival BCL2 proteins are frequently up‐regulated in tumour cells." (PMID 28548464, 2017). "In the canine mammary gland samples, Bcl-2, Bax, and Bad staining was diffusely cytoplasmic and it was observed in both tumor and healthy/hyperplastic tissues and in both epithelial/luminal and myoepithelial/basal cells." (PMID 28081183, 2017).
tumor (continued). "The 2HF treated tumor tissues also showed a decrease in anti-apoptotic protein BCL-2 and mesenchymal markers vimentin and fibronectin." (PMID 29088842, 2017). "Compared to the control group, both nsPEF- and everolimus-treated tumours showed increased expression of caspase 3, caspase 6, and Bax, and decreased expression of Bcl-2." (PMID 28054548, 2017). "Endostatin is an endogen inhibitor of angiogenesis which interacts with endothelial cell molecules, induces apoptosis by inhibiting anti-apoptotic proteins Bcl-2 and Bcl-xL and inhibits tumor growth." (PMID 28727816, 2017). "Although we did not provide the underlying mechanism how Bcl-2 suppress p21, it is very clear that liberated p21 from Bcl-2 can induce cell cycle arrest and performed the tumor suppressive role and that IPP-14 can promote p21 releasing from Bcl-2." (PMID 28423593, 2017). "KRAS and BCL2 oncogenes were highly expressed in tumor tissues, whereas the tumor suppressor PTEN gene was significantly downregulated." (PMID 29268752, 2017). "Disturbance of the ratio of Bcl-2/Bax and increase of cytochrome c level were found in the tumor tissues after AZOX treatment, which are in accordance with the in vitro results." (PMID 28567017, 2017). "This pro-apoptosis effect was due to Bcl-2 repression and expression of the pro-apoptotic proteins caspase 3 and Bax, which demonstrated the chemosensitization of these tumor cells to docetaxel in the presence of ginsenosides R3." (PMID 28352231, 2017). "To investigate the anti-tumor efficacy of BetA in vivo, we used IM-9 and IM-9/Bcl-2 as model tumor cells." (PMID 29113343, 2017). "Previous research found vorinostat in combination with Bcl-2 and Bcl-xL inhibitor ABT-263 shows strongly cooperate to overcome heterogeneity associated with response to HDACi across diverse tumour cell types." (PMID 29212192, 2017). "After treatment with berberine, the levels of PSA, AR, COX-2, Bcl-2 in tumor tissues were markedly decreased, and the expression of Caspase-3 was increased." (PMID 29029409, 2017). "Recently, a novel role of Runx2 in tumor cell survival became evident as studies reveal that Runx2 inhibited the apoptotic pathway by activating the expression of survivin and Bcl2." (PMID 28300755, 2017). "Bcl2 expression was decreased in tumor cells with miR-125b-5p, which further confirmed that miR-125b-5p down-regulates Bcl2." (PMID 28256505, 2017). "To date, there is limited experimental evidence suggestings the involvement of Bcl-2 in tumor EMT progression." (PMID 28032603, 2017). "Our studies showed the Bcl2-Beclin1 interaction was blocked in the presence of MA, suggesting that the anti-tumor effect of MA probably be exerted through autophagy regulation." (PMID 29088805, 2017). "Overall, this paclitaxel/vitamin C derivative composite nanoparticle system enhanced the therapeutic tumor suppression of PTX via a synergistic effect that reduces the Bcl-2/Bax ratio accompanied by promoting tubulin polymerization." (PMID 28856937, 2017). "An animal model derived from the Tca8113 cell line was used to further validate the role of Bcl-2/Twist1 depletion in suppressing tumor EMT and growth." (PMID 28032603, 2017). "For better understanding of the apoptosis efficacy of XIAP 3′UTR in vivo, we examined the expression of Bcl-2, Bax and Caspase-3 in tumor samples immunoreactivity." (PMID 28186968, 2017). "Studies have shown that up-regulation of BCL-xL increases the chemo-resistance of tumor cells and expression of Bcl-2 always correlates with sensitivity to anticancer drugs." (PMID 29029479, 2017).